TET2 (tet methylcytosine dioxygenase 2)
Diseases named in the same sentence as TET2 in open-access papers (continued):
Sharing a sentence is not in itself a finding about the gene and the disease.
leukemia (continued). "Targeting MBD6 may offer a therapeutic strategy for TET2‐mutant leukaemia." (PMID 40008496, 2025). "It is also known that TET2 mutations are among the most common in Clonal Hematopoiesis of Indeterminate Potential (CHIP), a condition where aging individuals develop hematopoietic clones without having full-blown cancer, but with an increased risk of cardiovascular disease and leukemia." (PMID 41440942, 2025). "Furthermore, the absence of TRAF6 in Tet2-deficient pre-leukemic cells has been shown to promote the transition to overt leukemia in mice." (PMID 38609495, 2024). "While certain mutations (e.g., DNMT3A, TET2, and ASXL1) are frequently observed in clonal hematopoiesis and seem to occur relatively early in leukemogenesis, others tend to emerge later during the progression of leukemia, they include mutations in FLT3, NRAS, and RUNX1." (PMID 37958832, 2023). "Also, they found a significant association between TET2 expression and FAB subtypes of leukemia." (PMID 36371552, 2023). "Indeed, leukemia progression was suppressed by treating AML cells with the PARP inhibitor olaparib in combination with vitamin C. Vitamin C-mediated restoration of TET2 in leukemic stem cells induces TET-mediated DNA oxidation associated DNA damage repair pathway activation." (PMID 36060265, 2022). "The relationship between vitamin C and TET activity has recently attracted attention in the context of leukaemia research, where vitamin C supplementation is being investigated as a form of epigenetic therapy to enhance TET2 activity in models of leukaemia characterised by decreased TET2 activity." (PMID 35163133, 2022). "Besides, in multivariate analysis, the impact of TET2 mutation on RFS remained significant; thus, TET2 mutation might be correlated with relapse of leukemia." (PMID 32970934, 2020). "Although TET2 has been studied most extensively in various types of leukaemia, in the current study, Tet2 expression increased with ageing and was inversely correlated with 5mC levels, which suggests that Tet2 might be responsible for the age-related accumulation of 5hmC." (PMID 28218666, 2017). "Recent works have shown that the absence of Dnmt3a or Tet2 in hematopoietic stem cells predisposes to leukemia formation, but that restoring the expression of Dnmt3a after the leukemia had developed did not revert the phenotype." (PMID 28425913, 2017). "Therefore, I predict that ascorbate supplementation to patients with myeloid neoplasms will most benefit those who, at baseline, have below-average ascorbate levels, irrespective of whether their leukemias carry TET2 mutations." (PMID 40213851, 2025). "In Haferlach leukemia samples, overexpression of TET1 and TET2 was identified, whereas TET3 downregulation was noted in Andersson leukemia samples." (PMID 39519332, 2024). "While the consequences of these PML/TET2 enforced epigenetic changes were not explored, one should note that in APL, two master genes involved in leukemia initiation or progression (DNMT3A and WT1) regulate the status of 5-methylcytosine, similar to TET2." (PMID 37382966, 2023).
leukemia (continued). "In this context, vitamin C-induced TET2 activity led to the accumulation of oxidized 5mCs and the recruitment of the BER machinery, increasing the sensitivity of leukemia cells to PARP inhibitors that block DNA repair." (PMID 36060265, 2022). "To examine the contribution of TET2 in shaping the methylation landscape, we first sequenced a panel of T- and B-ALL cell lines to assess fidelity to the parental leukemia subtypes." (PMID 35590059, 2022). "Vitamin C was shown to synergize with DNMTi treatment in a TET2-dependent manner to increase 5hmC, and drive DNA hypomethylation to further increase ERV expression and enhance apoptosis of leukemia and solid tumor cell lines." (PMID 34017357, 2021). "For this purpose, we ectopically expressed TET2 into both TET2WT (MEG-01 and CMK) and TET2MT (HEL) leukemia cell lines." (PMID 32895473, 2020). "In contrast, many mutations, including nonsense/missense, deletions and frameshift somatic in TET2 were identified in myelodysplastic syndrome (MDS) and other types of leukemia." (PMID 26869355, 2016). "The heterozygous combination of FLT3ITD, TET2, and DNMT3A leads to aggressive leukemia." (PMID 39078434, 2025). "To test our hypothesis, we performed qRT-PCR to quantify the effect of both drugs on the transcription of the three isoforms, TET1, TET2, and TET3, in U937 leukemia cells." (PMID 41516186, 2025). "Moreover, since it has been shown that vitamin C drives the expression of a TET2-dependent gene signature in human leukemia cell lines, we investigated, in the same cohort of AML patients and HDs, the TET2 transcripts level." (PMID 35832559, 2022). "Studies have shown that Tet2 elimination can change the epigenetic map of cells and promote the proliferation of CAR-T cells derived from a single cell clone, thereby promoting remission in leukemia patients and improving the efficacy of immunotherapy." (PMID 34222235, 2021). "To further expand the understanding of acetylation mediated increase in TET2 activity, we treated TET2WT (CMK) and TET2MT (HEL and SIG-M5) leukemia cell lines with specific P300/CBP inhibitors C64640 or HATi41 and also with the sirtuin activator SRT172042 in the presence and absence of AA." (PMID 32895473, 2020). "Consequently, TET2-disrupted CAR T cells were shown to display a central memory phenotype and induced long-term leukemia remission." (PMID 31001476, 2019). "In accordance to our data, it was found that low doses of vitamin C (300 μM) could enhance the effects of 2.5 μM DAC on the leukaemia cell lines HL60 and NB4, reducing proliferation, increasing apoptosis and enhancing TET2 activity." (PMID 30214687, 2018). "TET2 binds and activates WT1 target genes by increasing the 5hmC levels at the promoter regions of these specific sites in normal HSC, and therefore TET2 inhibits leukemia proliferation in a WT1-dependent manner." (PMID 26861406, 2016). "Recently, it was reported that the gene encoding TET2 but not TET1 and TET3 was frequently mutated, and it was identified as the relevant tumor suppressor gene, which is mutated in leukemia." (PMID 26366235, 2015). "We identified and validated somatic mutations, often affecting known leukemia (DNTM3A, TET2, and BCOR) in tumor-infiltrating leukocytes but not in the cancer cells of 7 of the 15 patients." (PMID 28721364, 2015). "Notably, one of the down-regulated microRNAs represented in low miR-188–5p expressers was miR-22, an unfavorable factor targeting TET2 in myelodysplastic syndrome (MDS) and leukemia." (PMID 25646775, 2015). "Importantly, expression of the most frequently mutated genes in T cell lymphoma or leukemia (i.e., DNMT3A, TET2, JAK, NOTCH1, CDKN2A, PTEN, and FBXW7) was not altered in miR-H18-BCMA CAR T cells." (PMID 35821635, 2022).
leukemia (continued). "TET2–/– THP1 cells have a higher sensitivity to Epag compared with the nontargeting gRNA THP1 control cells, suggesting that the inhibition of residual TET activity mostly coming from TET3 may be detrimental for TET2 mutant leukemia cells." (PMID 35085104, 2022). "Myb is known to promote the survival and proliferation of HSCs and leukemia stem cells; thus, we performed in vitro and in vivo assays, using Myb-depleted cells, to determine the impact of depleting Myb on the proliferation of HSPCs lacking p300 and TET2." (PMID 34622806, 2021). "Consistently, a recent study has shown that Tet2 depletion increases the intestinal permeability (especially the jejunum), leading to microbial leaky and chronic inflammation, which function as an extrinsic non-cell-autonomous factor for leukemia onset." (PMID 32616016, 2020). "Thus, our study highlights the contribution of factors that may enhance or attenuate AA effects on TET2 and provides a rationale for novel therapeutic approaches including combinations of AA with class I/II HDAC inhibitor or sirtuin activators in TET2MT leukemia." (PMID 32895473, 2020). "By contrast, all other tested somatic mutations detected in tumor-infiltrating leukocytes, including in known leukemia genes (DNMT3A, TET2, and BCOR) were not identified in breast cancer cells consistent with their origin in the leukocyte component." (PMID 28721364, 2015). "Notably, the binding of the W1291R mutant to non-TET2 loci is the first report that mutations in CRTET2 can change its genomic localization, potentially opening the prospect that genomic mis-localization of CRTET2 mutants to non-target loci could serve as a biomarker for leukaemia." (PMID 28130413, 2017).
acute myeloid leukemia (183 papers, 2010 to 2026). Acute myeloid leukemia (AML) is a group of neoplasms arising from precursor cells committed to the myeloid cell-line differentiation. "In acute myeloid leukemia, TET2 mutations or functional loss result in global DNA methylation abnormalities." (PMID 41403402, 2026). "TET2 is a frequently mutated gene in acute myeloid leukemia (AML) and glioblastoma and contributes to their pathogenesis." (PMID 41516186, 2025). "Mutations in the TET2 gene are frequently observed in hematological cancers, such as acute myeloid leukemia (AML), myelodysplastic syndromes (MDS), and chronic myelomonocytic leukemia." (PMID 40650308, 2025). "Statins have been found to reduce the risk of progression from myelodysplastic syndrome to acute myeloid leukaemia and have also shown efficacy in vitro against TET2 deficient AML cell lines." (PMID 40321277, 2025). "While modest inhibition of proliferation was observed in TET2 WT cell lines, almost complete proliferation blockade was observed for SKM-1 cells, an acute myeloid leukaemia (AML) cell line bearing a TET2 mutation, after MBD6 KD." (PMID 39358506, 2024). "Despite the high incidence of tet methylcytosine dioxygenase 2 (TET2) mutations in acute myeloid leukemia (AML), the prognostic implications of these mutations in three AML risk groups based on the 2022 ELN AML risk classification are still unclear." (PMID 38349460, 2024). "Acute myeloid leukemia with mutations in TET2 or IDH2 is sensitive to epigenetic therapy involving the inhibition of DNA methyltransferase activity using 5-azacytidine or the inhibition of mutant IDH2." (PMID 38929174, 2024). "Loss-of-function mutations of the TET2 gene are commonly detected in hematopoietic tumors, such as acute myeloid leukemia, chronic myelomonocytic leukemia, and peripheral T cell lymphomas." (PMID 37643007, 2023). "TET2 mutations are commonly seen in myeloid neoplasms, ranging from myelodysplastic and overlap syndromes to acute myeloid leukemias as well as in T-cell lymphomas." (PMID 34494161, 2022). "This study aimed to investigate the clinical and prognostic significance of TET2 single nucleotide polymorphism I1762V in patients with acute myeloid leukemia(AML)." (PMID 35405783, 2022). "TET2 loss of function mutations are frequently found in patients suffering from myeloid malignancies such as acute myeloid leukemia, myeloproliferative neoplasms, or myelodysplastic syndromes." (PMID 35159097, 2022). "Mutations in the TET2 gene are detected in a variety of myeloid malignancies, including acute myeloid leukemia (AML)." (PMID 35962058, 2022). "Dysfunction of TET2 is well-proved to be associated with acute myelocytic leukemia (AML), myelodysplastic syndromes (MDS) and other myeloid disorders." (PMID 33085059, 2021). "Nine months after first admission the patient developed acute myeloid leukemia with DNMT3a and TET2 mutations." (PMID 33708776, 2021). "Sequencing results in such patients have revealed the presence of heterogeneous TET2 mutations in 12–26% of patients with acute myeloid leukemia (AML), myelodysplastic syndrome (MDS) and myeloproliferative neoplasms (MPN)." (PMID 33643703, 2021). "In acute myeloid leukemia (AML) TET2 mutations have been observed to be mutually exclusive with IDH1, IDH2, and WT1 mutations, all of them showing a similar impact on the transcription profile." (PMID 33805247, 2021). "Using cBio Cancer Genomics Portal (cBioPortal) databases, we also found that mutation of TET2 was frequent in cancers, such as uterine cancer, acute myeloid leukemia, and melanoma." (PMID 33097695, 2020). "Evidence has proved that TET2 mutation is associated with leukemogenesis, drug response, and prognosis in acute myeloid leukemia (AML)." (PMID 32209730, 2020). "TET2 was identified as a tumor suppressor and mutations across the gene have been implicated in acute myeloid leukemia (AML), myeloproliferative neoplasms (MPN), and myelodysplastic syndrome (MDS)." (PMID 31614829, 2019).
acute myeloid leukemia (continued). "TET2 mutations are one of the earliest genetic alterations in the evolution of acute myeloid leukemia and chronic myelomonocytic leukemia." (PMID 31217902, 2019). "TET2 mutation has been closely linked to myeloid malignancies including myelodysplastic syndrome and acute myeloid leukemia in human." (PMID 30809228, 2019). "TET2 is mutated in several human cancers, including myeloid malignancies such as acute myeloid leukemia (AML)." (PMID 30319972, 2018). "Recently, it was reported that loss of Tet2 together with Flt3ITD induces acute myeloid leukemia (AML) in a mouse model." (PMID 29361987, 2018). "Two other TET2 SNPs, rs2454206 and rs3733609, have been shown to be either a prognosis marker in pediatric acute myeloblastic leukemia or a predisposition factor in myeloproliferative neoplasm harboring JAK2V617F mutation, respectively." (PMID 28881727, 2017). "For example, TET2 gene mutation and its catalytic inactivation are closely related to acute myeloid leukemia." (PMID 27835592, 2016). "TET2 is a methylcytosine dioxygenase that is frequently mutated in myeloid malignancies, notably myelodysplasia and acute myeloid leukemia." (PMID 25276435, 2014). "TET2 mutation is enriched amongst cases of myeloid malignancy occurring in approximately 12% of acute myeloid leukemia (AML) cases and up to 58% of mixed myeloproliferative neoplasms (MPN) and myelodysplastic syndromes (MDS)." (PMID 25276435, 2014). "Loss of function mutations of the TET2 gene are recurrently observed in myelodysplasia, myeloproliferative disorders and acute myeloid leukemia." (PMID 23533652, 2013). "Here, we describe somatic biallelic TET2 mutations in an elderly patient with acute myeloid leukemia (AML) that was chemoresistant to anthracycline and cytarabine but acutely sensitive to 5′-azacitidine (5′-Aza) hypomethylating monotherapy, resulting in long-term morphological remission." (PMID 36480300, 2023). "Furthermore, TET2 mutations often occur in hematological malignancies, with approximately 10% in acute myeloid leukemia, 30% in myelodysplastic syndrome, and 50% in chronic myelomonocytic leukemia." (PMID 33352824, 2020). "However, several studies evaluated other mutations in the TET2 gene related to the development of blast crisis and acute myeloid leukemia, which is currently an interesting line of research." (PMID 31208359, 2019). "Finally, investigators studying conversion of pre-leukemic acute myeloid leukemia (AML) cells with TET2 mutations to full-blown AML have identified a significant role of Ref-1/APE1 in this process." (PMID 28825044, 2017). "TET2 or IDH1/2 mutations are commonly observed in acute myeloid leukemia (AML)." (PMID 28039446, 2017). "TET2 mutations occur in 7–23% of patients with acute myeloid leukemia (AML)." (PMID 28039446, 2017). "Hydroxymethylation enzyme defects have previously been associated with hematological malignancies; mutations in TET2 were found in acute myeloid leukemia (AML) or chronic myelomonocytic leukemia (CMML) and induced loss of hydroxymethylation and were linked with poor prognosis." (PMID 27980696, 2016). "In addition, loss-of-function mutations in TET2 and a resultant reduction in 5-hmC are observed in myeloid malignancies, including acute myeloid leukemia (AML), chronic myelomonocytic leukemia and myelodysplastic syndrome." (PMID 27977763, 2016). "Loss-of-function mutations in TET2 have been reported in a variety of hematological malignancies including acute myeloid leukemias (AMLs), chronic myelomonocytic leukemia (CMML), myeloproliferative neoplasms (MPNs), myelodysplastic syndromes (MDS) and lymphoid malignancies." (PMID 24788138, 2014). "In addition, the mutation of TET2 in acute myeloid leukemia (AML) is associated with a decrease in 5 hmC content and, by the impairment of the demethylase pathway." (PMID 23873296, 2013). "TET2 null mutations are found in 22% of acute myeloid leukemia (AML)." (PMID 24152442, 2013).